PARP1 (poly(ADP-ribose) polymerase 1)
Diseases named in the same sentence as PARP1 in open-access papers (continued):
Sharing a sentence is not in itself a finding about the gene and the disease.
embryonal carcinoma (2 papers, 2016 to 2017). A non-seminomatous malignant germ cell tumor characterized by the presence of large germ cells with abundant cytoplasm resembling epithelial cells, geographic necrosis, high mitotic activity, and pseudoglandular and pseudopapillary structures formation. "A band corresponding to 89kDa- cleaved PARP-1 was detected in embryonal carcinoma cell line treated with cisplatin used as positive control." (PMID 28615629, 2017). "PARP1 positivity was the highest in GCNIS and among germ cell tumours its expression was higher in less differentiated subtypes of tumours, seminoma and embryonal carcinoma, with decreased positivity in more differentiated subtypes." (PMID 27487789, 2016).
endometrioid carcinomas (2 papers, 2013 to 2022). "Authors also observed that in most cases (except non-endometrioid carcinomas) PARP-1 expression positively correlated with progesterone receptor expression (p < 0.0001)." (PMID 36289716, 2022). "PARP-1 regulation of PR activity is of great interest in endometrioid carcinomas specifically, as expression of PARP-1 and PR is positively correlated at each pathologic stage of this cancer." (PMID 24350055, 2013).
endometriosis (2 papers, 2022 to 2024). The growth of functional endometrial tissue in anatomic sites outside the uterine body. "In endometriosis and adenomyosis, iron overload inhibits cell proliferation and promotes autophagic cell death via PARP1 (Poly (ADP-Ribose) Polymerase 1)/SIRT1 (Sirtuin 1) signaling in endometriosis and adenomyosis." (PMID 38397379, 2024). "What is more, PARP-1 expression was reduced in the subgroup of women with endometriosis and cabergoline intake." (PMID 36289716, 2022). "The authors observed that PARP-1 expression was higher in the neutrophils of endometriosis patients compared to healthy controls." (PMID 36289716, 2022). "This evidence of PARP-1 association with the immune response could be coherent with the immunological theory of endometriosis and suggests the possibility of another direction in the PARP-1 and endometriosis research." (PMID 36289716, 2022).
eosinophilia (2 papers, 2015 to 2017). "At this dose, the drug exerted a pronounced protection against the inflammatory burden induced by repeated OVA challenges including eosinophilia, mucus production, and AHR in a manner similar to that conferred by PARP-1 gene deletion." (PMID 26169874, 2015).
familial cancers (2 papers, 2013 to 2015). "Clinically, the focus of PARP-1 is as a target for the treatment of familial cancers, such as BRCA1/2 deficient breast and ovarian tumors." (PMID 24202328, 2013). "Here we have discussed the potential for using PARP-1 inhibition as treatment for not only familial cancers, but also cancers associated with chronic inflammation and high metabolism, which result in high levels of ROS." (PMID 24202328, 2013). "Interestingly, we found that susceptibility of non-familial cancers to PARP-1 inhibition may be through altered NFκB signaling." (PMID 24202328, 2013). "While clinical trials have been conducted for the use of PARP-1 inhibitors in the treatment of cancer, the focus of PARP-1 inhibition was concentrated on its use to obtain synthetic lethality in familial cancers, such as those with a BRCA1/2 mutated phenotypes." (PMID 24202328, 2013). "Therefore, it may be possible to use of PARP-1 inhibitors to not only treat familial cancers, but also to treat and even prevent cancers of non-familial origin, especially cancers associated with chronic inflammation." (PMID 24202328, 2013).
Hearing impairment (2 papers, 2023 to 2025). A decreased magnitude of the sensory perception of sound. "By pharmacologically inhibiting PARP-1, we demonstrated that it serves as a pivotal mediator of cisplatin-induced damage to HCs, with its activation closely associated with cisplatin-induced hearing loss." (PMID 40577815, 2025). "Overall, given the limited therapeutic options for blast-induced hearing loss and tinnitus, our results on the effect of 3AB on mouse auditory hair cells indicate that inhibition of PARP1 might be a potential therapeutic approach for blast injury of the cochlea and auditory pathway." (PMID 36949771, 2023). "Taken together, PARP-1 is considered a potential key target for the treatment of hearing impairment." (PMID 40577815, 2025). "Based on these findings, we propose that PARP-1- and AIF-mediated parthanatos plays a key role in cisplatin-induced hearing impairment." (PMID 40577815, 2025).
Hypoinsulinemia (2 papers, 2010 to 2024). A decreased concentration of insulin in the blood. "NICO inhibits PARP-1 over activation, preventing excessive NAD+ and ATP depletion, thereby reducing β-cell necrosis and resulting in partial insulin deficiency and hypoinsulinemia." (PMID 39766390, 2024).
infertile (2 papers, 2009 to 2024). "However, overactivation of PARP-1 represents an important mechanism of tissue damage in various pathological conditions related to oxidative stress, resulting in cell death by apoptosis, which contributes to OS-related infertility." (PMID 39902465, 2024). "Higher levels of PARP1, PARP2 and PARP9 were seen in ejaculated sperm from fertile men when compared to infertile men indicating a possible relationship between PARP and male infertility." (PMID 19961617, 2009).
inflammatory skin disorders (2 papers, 2021 to 2023). "Clinical data also support the role of these signaling pathways in PS, pointing to NAMPT and PARP1 as potential new therapeutic targets in treating inflammatory skin disorders." (PMID 37175698, 2023).
kidney cancer (2 papers, 2020 to 2022). Primary or metastatic malignant neoplasm involving the kidney. "When APE2 and PARP1 values were correlated, liver and uterine cancer samples showed more variability whereas very little spread occurred in breast and kidney cancer samples." (PMID 32111912, 2020). "PARP1 was upregulated in all cancer types except kidney cancer." (PMID 32111912, 2020).
lung squamous cell carcinoma (2 papers, 2018 to 2021). "MiSplice identified a conventionally annotated silent PARP1 mutation (p.S939S) in a lung squamous cell carcinoma (LUSC) patient that acts as a splice-site-creating variant by creating a de novo donor site." (PMID 29617666, 2018).
lymphoid leukemia (2 papers, 2025). A malignant lymphocytic neoplasm of B-cell or T-cell lineage involving primarily the bone marrow and the peripheral blood. "However, as we already reported, among 16 Ph + lymphoid leukemia cell lines we had tested, 10 cell lines were sensitive to olaparib, a poly (ADP-Ribose) polymerase- 1 (PARP- 1) inhibitor, suggesting that their HR pathway is somehow disrupted." (PMID 40208408, 2025).
lymphopenia (2 papers, 2017 to 2022). Reduction in the number of lymphocytes. "These two processes are altered in PARP-1/PARP-2-doubly-deficient proliferating lymphocytes leading to lymphopenia and impaired immune responses." (PMID 28181505, 2017). "Evidence derived from preclinical studies showed a role of PARP-1 and PARP-2 in T- and B-cell development, confirmed by the presence of lymphopenia in mice with dual PARP-1/2 deficiency likely caused by an accumulation of unrepaired DNA damages during IC proliferation." (PMID 35849879, 2022). "Notably, peripheral T-cell lymphopenia in PARP-1/PARP-2 doubly deficient mice results in functional impairment, as revealed by a dramatic defect in the humoral response to the T-dependent antigen TNP-KLH." (PMID 28181505, 2017).
mantle cell lymphoma (2 papers, 2022). Mantle cell lymphoma is a rare form of malignant non-Hodgkin lymphoma affecting B lymphocytes in the lymph nodes in a region called the ``mantle zone''. "Furthermore, the expression of PARP1 is related to a progressive course of indolent mantle cell lymphoma." (PMID 35449091, 2022). "For example, under SNS-032 treatment, the protein expression of cleaved PARP1 increased significantly in JeKo.1 but not in Granta 519; these cell lines are both human mantle cell lymphoma cell lines." (PMID 36313366, 2022).
mesothelioma (2 papers, 2021 to 2022). A usually malignant and aggressive neoplasm of the mesothelium which is often associated with exposure to asbestos. "The first results from a clinical trial performed to test the sensitivity to PARP-1 inhibition of BAP1- or BRCA1-deficient mesotheliomas have been published very recently." (PMID 34443328, 2021). "Furthermore, lower expression of CDK7, AKT1, PARP1 (p < 0.1), CCND2 (cyclin D2), CDK2, CDK4, BIRC5 (survivin), PCNA and CDH2 (N-cadherin) (p < 0.005) have been shown to result in longer median survival of patients with mesothelioma." (PMID 36304150, 2022).
monocytic leukemia (2 papers, 2020 to 2025). "Monocytic leukemia cells produce ROS, which kill T cells and NK cells by triggering poly (ADP-ribose) polymerase-1–dependent (PARP-1–dependent) apoptosis." (PMID 32911844, 2020). "Immature monocytic leukemia cells have been discovered to induce apoptosis in neighboring dysfunctional CD4/CD8+ T cells through the disruption of NADPH production, a process involved in the PARP‐1/PAR pathway." (PMID 39927613, 2025).
neuroendocrine carcinoma (2 papers, 2020 to 2021). A malignant neuroendocrine neoplasm composed of cells containing secretory granules that stain positive for NSE and chromogranin. "Our rationale for using PC3 was that neuroendocrine carcinomas have worse prognoses than adenocarcinomas, and that they are insensitive to androgen ablation, making them appropriate for the clinical context of PARP‐1 inhibitor use." (PMID 32342655, 2020).
neuroendocrine tumor (2 papers, 2014 to 2023). "PARP1 has a central role in transcriptional regulation of inflammatory mediators, both in neuroendocrine tumors and in CNS cells." (PMID 24243533, 2014). "177Lu-octreotate increases the activation of poly(ADP-ribose) polymerase-1 (PARP1), a DNA repair enzyme, after internalization in SSTR2-expressing and SSTR5 neuroendocrine tumor cells." (PMID 38140100, 2023).
non-alcoholic steatohepatitis (2 papers, 2018). "Additionally, PARP1 inhibitors have been shown to mitigate the effects of liver inflammation, fibrosis, and alcoholic and non-alcoholic steatohepatitis, which are all critical steps toward the progression of liver cancer." (PMID 30271949, 2018).
oropharyngeal carcinoma (2 papers, 2021 to 2022). Carcinoma, predominantly squamous cell, arising from the epithelial cells of the oropharynx. "These investigations followed studies showing PARP1 overexpression in oral and oropharyngeal cancer." (PMID 35267438, 2022). "As the HPV status affects DNA double-strand break repair, we aimed to address if the HPV status had an effect on PARP1 overexpression and therefore on [18F]PARPi uptake in oral and oropharyngeal cancer." (PMID 34194286, 2021). "In order to investigate the expression of PARP1 in oropharyngeal cancer, HPV-negative (n = 7) and HPV-positive (n = 18) samples were derived from patients' posttransoral resection of oropharyngeal tumors." (PMID 34194286, 2021). "In order to confirm the correlation of the HPV status with cellular and molecular mechanisms underlying favorable prognosis, we investigated γH2AX, RAD51, and PARP1 protein expressions in HPV-positive and HPV-negative cell lines and oropharyngeal carcinoma patient samples." (PMID 34194286, 2021). "Another study found that human papilloma virus (HPV)-positive and negative oropharyngeal cancer cells showed similar PARP1 expression and [18F]PARPi uptake, suggesting the tracer as an HPV-independent imaging tool for imaging in oropharyngeal cancer patients." (PMID 35267438, 2022).
osteoporosis (2 papers, 2021 to 2023). A condition of reduced bone mass, with decreased cortical thickness and a decrease in the number and size of the trabeculae of cancellous bone (but normal chemical composition), resulting in increased fracture incidence. "In this regard, PARP1 and its PARylating activity exert influence over osteoclast differentiation and bone remodeling via NF-κB dependent transcription of IL-1β, and glucocorticoid-induced osteoporosis is a consequence of the inhibition of IL-1 production." (PMID 37087471, 2023). "There are other examples where PARP1 inhibition alleviated age-related cellular and tissue dysfunction and could be a potential therapeutic option for osteoporosis." (PMID 33805567, 2021).
pediatric cancers (2 papers, 2020 to 2022). "However, PARP1 has been shown to increase the antitumor activity of temozolomide and topotecan in preclinical studies, including models of pediatric cancers." (PMID 32345117, 2020).
perinatal asphyxia (2 papers, 2014). A disorder caused by a lack of blood flow or gas exchange to or from the fetus in the period immediately before, during, or after the birth process. "DNA damage elicited by perinatal asphyxia implies PARP-1 overactivation, promoting NF-κB translocation and expression of proinflammatory cytokines, a phenomenon associated with microglial migration toward the site of neuronal injury." (PMID 24723845, 2014). "Recent studies have attributed a possible role for poly(ADP-ribose) polymerase-1 (PARP-1), whose overactivation could induce neuronal cell death, whereas its inhibition by nicotinamide might protect against neuronal damage induced by perinatal asphyxia." (PMID 24783208, 2014).
peritoneal carcinoma (2 papers, 2017 to 2018). A peritoneum cancer that is located in the inside of the abdomen. "Another PARP inhibitor selective for PARP-1 and PARP-2, Niraparib, went under a phase I study (42 ovarian/peritoneal cancer patients) and the preliminaries antitumor results were 8 PR and 2 SD among the 20 BRCA mutations carrier patients while being 5 PR and 3 SD among the 22 WT BRCA patients." (PMID 28008141, 2017).
peritonitis (2 papers, 2016 to 2022). Inflammation of the peritoneum (tissue that lines the abdominal wall and covers most of the organs in the abdomen). "To verify above findings of PARP-1 in mediating NLRP3 activation in animals, we used the peritonitis model in WT and Parp-1−/− mice." (PMID 35098371, 2022).
pleural mesothelioma (2 papers, 2013 to 2018). A neoplasm that arises from the mesothelial cells of the pleura. "In this study we have examined the possible use of the small-molecule organometallic compound RAPTA-T as a tumor vascular modulation agent in pleural mesothelioma and describe a possible mechanism of action through PARP-1 inhibition." (PMID 29980753, 2018).
Retinal Diseases (2 papers, 2021 to 2024). "PARP1, activated by reactive oxygen species, was proven to be involved in inflammation, cell death, and retinal disease progression." (PMID 33747106, 2021). "The inhibition of PARP-1 expression may also be an important target point in pharmacological research and shows promising results in the treatment of different retinal diseases." (PMID 39458649, 2024).
retinal ischemia (2 papers, 2024 to 2026). A ischemic disease that involves the retina. "Accumulating evidence from multiple studies suggests that poly(ADP-ribose) polymerase 1 (PARP1), an enzyme critical for DNA repair and genomic stability, plays a significant role in retinal ischemia–reperfusion injury by contributing to oxidative stress, inflammation, and neuronal apoptosis." (PMID 39337931, 2024). "In retinal ischemia/reperfusion and optic nerve injury models, HRS mitigated oxidative stress and apoptosis through pathways that regulate PARP-1 overactivation and reduce lipid peroxidation." (PMID 41557063, 2026).
rotator cuff tear (2 papers, 2022 to 2024). "In a PARP-1 knockout mice rotator cuff tear model a significant reduction of muscle atrophy and fatty infiltration was observed in the PARP-1 deficient mice." (PMID 38668315, 2024). "Previous results demonstrated that the absence of PARP-1 activity led to an improvement in muscle structural abnormalities as well as in other events such as apoptosis, atrophy, and inflammation in a model of rotator cuff tear in mice." (PMID 35740560, 2022).
silicosis (2 papers, 2022 to 2024). Silicosis is a respiratory disease caused by breathing in (inhaling) silica dust. "Moreover, bioinformatics analysis identified that the lncRNA MSTRG.43085.16/PARP1 pathway played a crucial role in the process of silicosis." (PMID 38397383, 2024).
skin inflammation (2 papers, 2023 to 2025). "The role of PARPs in skin inflammation, however, is a sparsely studied topic, and studies so far focused on PARP1." (PMID 37351597, 2023). "The researchers concluded that hyperactivation of PARP1, triggered by reactive oxygen species-induced DNA damage and fuelled by NAD+ derived from visfatin/NAMPT, led to skin inflammation through a form of programmed cell death known as parthanatos." (PMID 41002974, 2025).
teratoma (2 papers, 2016 to 2018). A non-seminomatous germ cell tumor characterized by the presence of various tissues which correspond to the different germinal layers (endoderm, mesoderm, and ectoderm). "In the present study, our finding indicated that, transfection with Oct4/Sox2/Klf4/Parp1(OSKP) were capable of the generation of OSKP-iPSCs that formed smaller teratoma than iPSCs reprogrammed with the conventional reprogramming factors Oct4/Sox2/Klf4/c-Myc." (PMID 29719629, 2018).
testicular cancer (2 papers, 2019 to 2021). A primary or metastatic malignant neoplasm that affects the testis. "However, the caveat to this study was that the original PARP-1 −/− mice (Jackson Laboratories # 002779) were obtained from parental 129Sv background mice, which demonstrate a proclivity to developing testicular cancer." (PMID 30691122, 2019).
Thrombocytopenia (2 papers, 2015 to 2025). A reduction in the number of circulating thrombocytes. "Of particular concern is thrombocytopenia, as PARP1 is expressed in the megakaryocyte lineage, and PARP inhibition can reduce platelet formation." (PMID 40687421, 2025). "MK-4827 (niraparib), an orally available compound, demonstrating strong PARP-1 and PARP-2 inhibitory activity has the side effects of nausea, vomiting, fatigue and thrombocytopenia." (PMID 25606064, 2015).
abdominal aortic aneurysm (1 paper, 2023). Enlargement and ballooning of the vessel that supplies arterial blood to the abdomen, pelvis and legs. "Genetic deletion of PARP1 has been found to prevent abdominal aortic aneurysm formation in an animal model." (PMID 36835806, 2023).
actinic keratosis (1 paper, 2025). A precancerous lesion of the skin composed of atypical keratinocytes. "In group 1, the mean PARP1 proportion of positivity ranged from 0.248 ± 0.124 in actinic keratosis lesions (premalignant) to 0.877 ± 0.107 in BCC lesions." (PMID 40506240, 2025). "We demonstrated significantly higher PARP1 expression in BCC lesions compared with benign, precancerous (actinic keratosis), and inflammatory lesions, which would result in lower PARPi-FL binding and signaling in the latter compared with BCC lesions in vivo." (PMID 40506240, 2025).
acute tubular necrosis (1 paper, 2009). "The present study explored the hypothesis that increased tubular expression of PARP-1 contributes to delayed renal function in suboptimal ECD kidney allografts and in non-ECD allografts that develop posttransplant acute tubular necrosis (ATN)." (PMID 19784367, 2009).
allergic rhinitis (1 paper, 2020). Inflammation of the nasal mucous membranes caused by an IgE-mediated response to external allergens. "The regulation of miR-92a-3p modified the transcription of KAT2B and PARP1, which played an important role in the development of combined allergic rhinitis and asthma syndrome." (PMID 31924195, 2020).
amyloidosis (1 paper, 2026). A disorder characterized by the localized or diffuse accumulation of amyloid protein in various anatomic sites. "In vivo, PARP1 knockout in the 5XFAD mouse model of amyloidosis led to reduced amyloid plaque burden, preserved synaptic and neuronal integrity, attenuated glial activation and neuroinflammation, and rescued cognitive deficits." (PMID 42139290, 2026).